MFRP (membrane frizzled-related protein)
Description:
May play a role in eye development.
Synonyms: FLJ30570; rd6; NNO2; C1QTNF5; CTRP5; MCOP5
Tractability: Antibody: UniProt places it where antibodies can reach, with medium confidence; UniProt predicts a signal peptide or a membrane-spanning region; its Gene Ontology location is reachable by antibodies, with medium confidence.
Gene: Protein-coding gene on chromosome 11 (119,338,942 to 119,346,705, reverse strand). Ensembl gene ENSG00000235718.
Subcellular location: Apical cell membrane
Gene Ontology:
Molecular function: protein binding
Biological process: embryo development ending in birth or egg hatching
Cellular component: membrane; apical plasma membrane
Genetic constraint (gnomAD): Loss-of-function variants: 74 observed, 68.69 expected, observed/expected ratio (o/e) 1.08, 90% interval 0.89 to 1.31. The upper end of that interval is the gene's LOEUF score, 1.31, which puts it in group 5 of 6, group 1 being the genes least tolerant of losing a copy. Missense variants: 838 observed, 765.56 expected, observed/expected ratio (o/e) 1.09, 90% interval 1.03 to 1.16. Synonymous variants: 336 observed, 300.9 expected, observed/expected ratio (o/e) 1.12, 90% interval 1.02 to 1.22.
Homologues: Orthologues: chimpanzee MFRP (99% identical), macaque MFRP (87% identical), dog MFRP (84% identical), rabbit MFRP (83% identical), pig MFRP (83% identical), guinea pig MFRP (78% identical), mouse Mfrp (70% identical), rat Mfrp (67% identical), tropical clawed frog mfrp (42% identical), zebrafish mfrp (41% identical). Paralogues in human: CNTNAP3 (18% identical), CNTNAP5 (18% identical), CNTNAP3B (18% identical), CNTNAP2 (17% identical), CNTNAP4 (17% identical), CUZD1 (17% identical), F8 (17% identical), CNTNAP1 (17% identical), HEPH (16% identical), HEPHL1 (16% identical), NRXN2 (16% identical), F5 (16% identical), and 23 more.
Diseases named in the same sentence as MFRP in open-access papers:
MFRP is named in the same sentence as 37 diseases in open-access papers, as found by Europe PMC text mining. Sharing a sentence is not in itself a finding about the gene and the disease. The quoted sentences say what the papers report.
nanophthalmos (36 papers, 2008 to 2025). "Mutations in the MFRP gene cause nanophthalmos, a developmental defect manifested by abnormally short axial eye length, in both humans and mice." (PMID 40249779, 2025). "Severe MFRP gene mutations result in recessive nanophthalmos, and it appears that the MFRP gene's embryonic function is essential for the eye to develop fully at birth." (PMID 39286000, 2024). "Here, in this paper, we identified four homozygous variants and one complex heterozygous variants in the MFRP gene in five Chinese families and concluded that the MFRP-nanophthalmos encompass a features of distinct phenotypic diversity." (PMID 39076172, 2024). "In summary, we described detailed ocular abnormities of an isolated microphthalmia patient confirmed by a novel mutation in the MFRP gene with recessive inheritance in a consanguineous marriage family." (PMID 35402469, 2022). "Yellowish-white dots associated with MFRP mutations have been reported in nanophthalmos patients, and the author referred to these lesions as retinal degeneration or retinal atrophy." (PMID 35402469, 2022). "Our study also expanded the spectrum of known MFRP mutations and provided photographic records of patients with microphthalmia." (PMID 35402469, 2022). "Mutations in human PRSS56 and MFRP are responsible for nanophthalmos that exhibit a severe reduction in ocular axial length, and high hyperopia." (PMID 33755662, 2021). "Mutations in PRSS56 and MFRP constitute a major cause of nanophthalmos, a condition characterized by severe reduction in ocular axial length/extreme hyperopia." (PMID 33755662, 2021). "Previous studies have identified PRSS56 and MFRP mutations as a major cause of nanophthalmos, a condition characterized by severe ocular size reduction and extreme hyperopia, suggesting that these factors play a critical role in ocular growth." (PMID 33755662, 2021). "For example, in Chinese populations, variants in two of the most commonly mutated genes in isolated recessive nanophthalmos, MFRP and PRSS56, account for less than 6% and 8% of cases, respectively." (PMID 31048900, 2019). "This characterization is further supported by mutations in MFRP in different families with nanophthalmos, high hyperopia, or posterior microphthalmia." (PMID 31172260, 2019). "A significant number of cases of recessive nanophthalmos have been assigned to mutations in the membrane-type frizzled-related protein gene (MFRP, OMIM 606227)." (PMID 29862063, 2018). "Mutations in human MFRP (membrane-type frizzled-related protein) gene cause hyperopia and nanophthalmos." (PMID 29170418, 2017). "Hyperopia (farsightedness) is a common and significant cause of visual impairment, and extreme hyperopia (nanophthalmos) is a consequence of loss-of-function MFRP mutations." (PMID 29170418, 2017). "Studies on the postnatal progression of refractive error in nanophthalmos patients having mutations in MFRP suggest a role of MFRP protein in embryonic ocular growth and postnatal emmetropization." (PMID 25357075, 2014). "The combination of features observed in this family closely resembles the nanophthalmos- retinitis pigmentosa-foveoschisis-optic disc drusen disease complex previously associated with MFRP mutations." (PMID 23077403, 2012). "MFRP is thought to play a role in eye development, as mutations in the gene that codes for this protein have been associated with nanophthalmos, retinitis pigmentosa (RP), and other degenerative disorders." (PMID 23077403, 2012). "Previous studies associated mutations in the MFRP gene with the syndrome nanophthalmos-retinitis pigmentosa-foveoschisis-optic disc drusen." (PMID 23077403, 2012). "As human MFRP mutations result in nanophthalmos and mutations in the orthologous Mfrp gene causes the recessive mouse retinal degeneration rd6, these authors searched for MFRP mutations as a source for this novel phenotype." (PMID 19753314, 2009).
nanophthalmos (continued). "In this work, we describe the clinical and genetic features of a new familial case of the syndrome of nanophthalmos-retinitis pigmentosa-foveoschisis-optic disc drusen in which two distinct MFRP mutations, including a novel nonsense change, were demonstrated." (PMID 19753314, 2009). "Mutations in the membrane-type frizzled-related protein (MFRP) gene have been identified in patients with pathologic high hyperopia associated with nanophthalmos or microphthalmia." (PMID 19169412, 2009). "CHX10, a retinal homeobox gene associated with microphthalmia, and MFRP, the membrane-type frizzled-related protein gene underlying recessive nanophthalmos, represent good candidate genes for PACG due to the association with small eyes." (PMID 18648522, 2008). "Mutations in the MFRP gene have also been reported in a distinct autosomal recessive ophthalmic syndrome characterized by microphthalmos, retinitis pigmentosa, foveoschisis, and optic disc drusen." (PMID 18334955, 2008). "The membrane-type frizzled-related protein (MFRP) gene is selectively expressed in the retinal pigment epithelium and ciliary body, and mutations of this gene cause nanophthalmos." (PMID 18334955, 2008). "Recently, four independent mutations were identified in the membrane-type frizzled-related protein (MFRP) gene associated with nanophthalmos, a rare disorder of eye development characterized by extreme hyperopia (farsighted refractive error)." (PMID 18334955, 2008). "The risk of this second vision-threatening pathology, particularly angle closure glaucoma, may be higher than that of the general population (1.1%) in some IRD genotypes (e.g., BEST1, CRB1, MFRP) associated with microphthalmia/nanophthalmos." (PMID 41465105, 2025). "Notably, as early as 2009, studies have shown that certain clinical phenotypes of nanophthalmos caused by MFRP mutations are correlated with age." (PMID 39076172, 2024). "Nanophthalmos can occur in association with optic disc drusen, foveoschisis, and retinitis pigmentosa, as an autosomal recessive syndrome linked to mutations in the MFRP gene." (PMID 37752465, 2023). "Our study further broadens the mutation and phenotype spectrum of the MFRP gene in microphthalmia." (PMID 35402469, 2022). "Genes such as PRSS56 (and MFRP), for which loss of function causes nanophthalmos, have been considered potential targets for slowing the progression of myopia, because reducing their functional activity may prevent further ocular elongation." (PMID 34698770, 2021). "While MFRP mutations have been linked to nanophthalmos and microphthalmia, the function of the MFRP protein is unknown." (PMID 29170418, 2017). "MFRP mutations in humans are also associated with posterior microphthalmia characterized by abnormal posterior segment size leading to hyperopia and cause recessive nanophthalmos." (PMID 25357075, 2014). "There is considerable genetic overlap between nanophthalmos and both hyperopia and angle closure—with mutations being identified in the NNO1 (nanophthalmos 1), and MFRP (membrane-type frizzled-related protein) genes." (PMID 39337937, 2024). "Five genes (MFRP, TMEM98, PRSS56, BEST1, and CRB1) and two loci have been implicated in familial forms of nanophthalmos." (PMID 39286000, 2024). "To date, the following six genes, PRSS56, MFRP, TMEM98, CRB1, BEST1 and MYRF, have been reported to be associated with the development of nanophthalmos." (PMID 39076172, 2024). "To date, six genes (PRSS56, MFRP, TMEM98, CRB1, BEST1, and MYRF) have been implicated in familial forms of nanophthalmos, with PRSS56 and MFRP mutations being the most prevalent among multiple cohorts." (PMID 33755662, 2021). "We have defined the diagnostic yield of sequencing the coding variants in PRSS56, MFRP, TMEM98, MYRF, CRB1, and BEST1 in a large cohort of patients with nanophthalmos and high hyperopia." (PMID 33203948, 2020).
nanophthalmos (continued). "While six genes have been implicated in this hereditary condition (MFRP, PRSS56, MYRF, TMEM98, CRB1,VMD2/BEST1), the relative contribution of these to nanophthalmos or to less severe high hyperopia (≥ + 5.50 spherical equivalent) has not been fully elucidated." (PMID 33203948, 2020). "To date, five genes (i.e., MFRP, TMEM98, PRSS56, BEST1, and CRB1) and two loci have been implicated in familial forms of nanophthalmos." (PMID 29862063, 2018). "Single-gene deletions and mutations affecting the ability to produce proteins and enzymes such as SOX2, MFRP, ALDH1A3, STRA6, PAX2, and OTX2, have been identified as causing isolated microphthalmia and anophthalmia and syndromic forms." (PMID 30153864, 2018). "Genetic mutations are associated with nanophthalmos according to some reports, which described associations with the serine protease gene (PRSS56) and membrane frizzled-related protein gene (MFRP)." (PMID 28057069, 2017). "As major causative genes for simple microphthalmia, CHX10 (Ceh10 homeodomain gene; OMIM 142993), PAX6 (Paired box gene 6; OMIM 607108), and MFRP (Membrane-type frizzled-related protein; OMIM 606227) probably induce the failure of ocular differentiation." (PMID 19452014, 2009). "To study the role of MFRP in eye biology, we utilized the retinal-degeneration-6 (rd6, Mfrprd6) mouse model, which displays many features in common with human ocular disease, including retinal degeneration and nanophthalmos." (PMID 40249779, 2025). "Furthermore, the membrane frizzled-related protein (MFRP) gene was related to nanophthalmos while the hepatocyte growth factor (HGF) gene was reported to be associated with hyperopia, and both nanophthalmos and hyperopia are important risk factors for PACG." (PMID 30348125, 2018). "Recently, membrane frizzled-related protein (MFRP) mutations were identified in patients with nanophthalmos associated with or without retinal disfunction." (PMID 22799444, 2012). "Previously, MFRP mutations were identified in subjects with nanophthalmos and high hyperopia but without retinal dysfunction." (PMID 19753314, 2009). "It is still not known why some MFRP mutations cause isolated nanophthalmos, while others trigger the nanophthalmos-retinitis pigmentosa-foveoschisis-optic disc drusen complex." (PMID 19753314, 2009). "In this study, mutation screening of the MFRP gene revealed no sequence variants that would implicate this gene in the development of moderate to high hyperopia, isolated microphthalmia, isolated anophthalmia, or high-grade myopia." (PMID 18334955, 2008). "MFRP null homozygotes frequently develop angle-closure glaucoma, cystoid macular edema, and serous retinal detachment, all conditions that are often related to hyperopia and microphthalmia." (PMID 18781223, 2008). "Four loci for nanophthalmos, i.e., NNO1 for autosomal dominant, NNO2 for autosomal recessive, NNO3 for autosomal dominant, and NNO4 for autosomal dominant, have been mapped, in which mutations in MFRP are responsible for NNO2 while those in TMEM98 are responsible for NNO4." (PMID 31172260, 2019). "Although the microphthalmia/anophthalmia cohort in this study could be considered developmental, we did not observe any mutations in the MFRP gene in this cohort." (PMID 18334955, 2008). "While the previously reported MFRP mutations in isolated nanophthalmos and syndromic microphthalmia may not directly influence axial length programming, the resultant loss of MFRP interaction involved in axial length regulation could lead to reduced eye size in those phenotypes." (PMID 18334955, 2008). "The membrane frizzled-related protein (MFRP) has been proposed as a probable candidate gene for extreme hyperopia and nanophthalmos, which are factors for angle-closure glaucoma." (PMID 18781223, 2008). "Thus far, genes identified in Mendelian cases of nanophthalmos have different roles in the retina (PRSS56, CRB1) and the retinal pigment epithelium (BEST1/VMD2, MFRP)." (PMID 31048900, 2019).
retinal degeneration (21 papers, 2009 to 2025). Degeneration of the retina. "In the mouse retina, a single injection of v3 PE3-eVLPs precisely corrected a pathogenic 4-bp deletion in the rd6 model of retinal degeneration, restoring production of full-length MFRP protein." (PMID 38191664, 2024). "Autosomal recessive retinitis pigmentosa (RP), one of the most common forms of inherited retinal degeneration, is caused mostly by defects in Membrane Frizzled-Related Protein (MFRP)." (PMID 34067183, 2021). "Mutations in human MFRP and mouse Mfrp lead to retinal degeneration in both species and have been associated with a decrease in axial length in humans." (PMID 25357075, 2014). "Further advance in the knowledge of MFRP molecular structure and function came from the study of an animal model of MFRP mutations, the retinal degeneration 6 mouse (rd6 mouse)." (PMID 23112574, 2012). "It was well documented that mutations in the MFRP gene cause a variety of vision disorders, including hyperopia, acute angle-closure glaucoma, retinitis pigmentosa, retinal folds, macular edema, retinal cysts, and retinal degeneration." (PMID 39372898, 2024). "MFRP mutations could be responsible for other inherited human diseases combining abnormally sized eyes and retinal degeneration." (PMID 35402469, 2022). "Nevertheless, the microarray and qRT-PCR data on Mfrprd6 and other retinal degeneration mutants suggest a broad and possibly unique role for MFRP protein in postnatal development of the RPE and retina." (PMID 25357075, 2014). "The MFRP gene was initially associated only with high hyperopia and reduced axial length, but not with retinal degeneration." (PMID 39076172, 2024). "MFRP mutations could cause a spectrum of retinal alterations, including patients with aggressive retinal degeneration starting in infancy as well as patients with no symptoms in elderly age." (PMID 23112574, 2012). "The absence of MFRP in Mfrprd6 RPE cells appears to cause the OSs to develop abnormally, and, combined with the observed in vivo impairment of RPE phagocytosis leads in turn to progressive retinal degeneration." (PMID 25357075, 2014).
hyperopia (19 papers, 2008 to 2025). A refractive error in which rays of light entering the eye parallel to the optic axis are brought to a focus behind the retina, as a result of the eyeball being too short from front to back. "Mutations in MFRP are associated with autosomal recessive nonsyndromic nanophthalmos, leading to severe hyperopia and early-onset retinitis pigmentosa, frequently accompanied by foveoschisis and optic-nerve-head drusen." (PMID 40249779, 2025). "Mutations in MFRP are associated with autosomal recessive nonsyndromic nanophthalmos, leading to severe hyperopia and early-onset retinitis pigmentosa." (PMID 40249779, 2025). "Conversely, MFRP, a gene associated with hyperopia, has interestingly been found to be expressed in the CE cells in zebrafish and in mice, and mutations in MFRP are associated with retinal thinning of all retinal cell layers." (PMID 34207050, 2021). "Mutations in MFRP are known to cause autosomal recessive nanophthalmos, characterized by short axial length, a high degree of hyperopia, increased lens/eye volume ratio, and small corneal diameter." (PMID 22933837, 2012). "Mutations in the Membrane-type frizzled protein (MFRP) gene cause autosomal recessive nanophthalmos, which is characterized by short axial length, a high degree of hyperopia, a high lens/eye volume ratio, and a small corneal diameter." (PMID 22933837, 2012). "Mutations in MFRP were reported to cause autosomal recessive nanophthalmos, which is characterized by short AL, a small corneal diameter, a high lens/eye volume ratio, and a high degree of hyperopia." (PMID 30348125, 2018). "Homozygous MFRP mutation carriers have a shorter axial length than normal eyes, with an increase in both choroidal and scleral thickness, which in turn leads to axial hyperopia." (PMID 22933837, 2012). "We sought to investigate whether sequence variants of MFRP are associated with less severe forms of hyperopia, other extreme forms of limited eye growth and development or high myopia and whether the MFRP gene plays a role in regulating ocular axial length in general." (PMID 18334955, 2008). "Several genes (e.g., BEST1, CRB1, MFRP, PRSS56 and TMEM98) which have roles in both foetal ocular development and post-natal outer retinal maintenance, can be associated with high hyperopia and short axial length." (PMID 41465105, 2025). "In conclusion, five novel sequence variations of MFRP were identified in the Chinese population where two of these novel variations were only present in patients with physiologic high hyperopia." (PMID 19169412, 2009). "Although it is less possible for the c.496C>G variation of MFRP to account for hyperopia, the recognition of this missense variation in the short tract of exon 5 in MFRP will help further the understanding of the role of this area in the function of MFRP." (PMID 19169412, 2009). "In conclusion, sequence variants of the MFRP gene do not appear to be associated with either the less severe forms of hyperopia, extreme forms of limited eye growth and development, or high myopia." (PMID 18334955, 2008). "Sequence variants of the MFRP gene do not appear to be associated with either the less severe forms of hyperopia, extreme forms of limited eye growth and development, or high myopia." (PMID 18334955, 2008). "Interestingly, (high) hyperopia (MFRP, MYO7A, BEST1) was more common in this group than myopia." (PMID 41465105, 2025). "Apart from MFRP and TMEM98, high hyperopia is a frequent sign in other ocular or systemic diseases associated with mutations in several following genes, including PRSS56, CRB1, LCA5, IFT140, and KERA." (PMID 31172260, 2019).